BACH1 (BACH transcriptional regulator 1)
Diseases named in the same sentence as BACH1 in open-access papers (continued):
Sharing a sentence is not in itself a finding about the gene and the disease.
breast tumors (9 papers, 2006 to 2025). "Using IHC assays, we detected BACH1 expression in breast tumors collected and processed in our facility." (PMID 40710214, 2025). "Our data suggested that BACH1 levels were particularly abundant in basal-like breast tumors from Black women, highlighting BACH1 as a distinct patient race-related biomarker." (PMID 40710214, 2025). "In many tumor types, including breast tumors, BACH1 regulates transcriptomes to facilitate cancer cell migration, invasion, and metastasis." (PMID 40710214, 2025). "Prior research found that BACH1 mRNA expression levels were highest in the basal-like subtype of breast tumors." (PMID 40710214, 2025). "In our comprehensive analyses of BACH1 and MCT1 expression in breast tumors using IHC assays, we observed substantial increased expression levels of BACH1 in the tumors from Black patients, particularly in the basal-like breast tumors." (PMID 40710214, 2025). "In our study, we evaluated the expression levels of BACH1 or MCT1 in breast tumor tissues to identify them as useful biomarkers." (PMID 40710214, 2025). "A positive association between BACH1 and MCT1 was detected in breast tumors among Black women, whereas a null association was found in tumors among White women." (PMID 40710214, 2025). "The results revealed a marked increase in BACH1 expression in breast tumors and metastatic tumors compared to normal breast tissues." (PMID 38838145, 2024). "Next, we analyzed breast tumor data from the Cancer Genome Atlas (TCGA) patient cohorts (n = 980) for BACH1, MCT1, and LDHB mRNA expression." (PMID 35406740, 2022). "The downstream genes of lactate catabolic pathways, LDHA and LDHB, also showed potential inverse correlations with BACH1 expression in breast tumors." (PMID 35406740, 2022). "BACH1 supports aerobic glycolysis by inhibition of mitochondrial electron transport chains (ETC) gene expression in breast tumors." (PMID 33809182, 2021). "BACH1, which we recently identified as an inhibitor of mitochondrial metabolism that can be targeted independently in ~30% of breast tumors, is shown here to be a transcriptionally-regulated and pro-invasive mediator of the stress MAPK network." (PMID 33973518, 2021). "A surprising finding in our study was that BACH1 expression in breast tumors differs by race." (PMID 40710214, 2025). "Importantly, BACH1 expression was significantly higher in tumors from Black women compared to those from White women, as well as in the basal-like subtype of breast tumors from Black women." (PMID 40710214, 2025). "Importantly, BACH1 expresses significantly higher in tumors from Black women than White women, as well as in the basal-like subtype of breast tumors from Black women." (PMID 37461502, 2023). "Therefore, we examined whether BACH1 expression levels in breast tumors correlate with patients’ age in our cohort." (PMID 40710214, 2025). "We further assessed whether BACH1 expression levels differed by the breast tumor subtypes." (PMID 40710214, 2025). "Thus, we immediately determined whether BACH1 protein expression levels were accessible via IHC analysis using the breast tumor tissues." (PMID 40710214, 2025). "However, the clinical relevance of BACH1 expression in breast tumors remains poorly understood." (PMID 40710214, 2025). "Our patient tumor cohort is highly valuable since it contains a similar number of patients of each race to investigate BACH1 and MCT1 expression in breast tumors." (PMID 40710214, 2025). "Using Spearman’s rank correlation analyses, we observed a positive correlation (0.376, p < 0.001) between BACH1 and MCT1 in total breast tumors (N = 114)." (PMID 40710214, 2025). "The heme-regulatory transcriptional factor BACH1 promotes the epithelial to mesenchymal transition (EMT), invasiveness, and migration of cancer cells, as well as the metastasis of breast tumors." (PMID 40710214, 2025).
breast tumors (continued). "Consistently, gene expression data from clinical breast tumor samples revealed that, although RKIP correlates inversely with BACH1 overall, the two transcripts cease to correlate when BACH1 surpasses a threshold, as in our cell line experiments." (PMID 37231268, 2023). "BACH1 is expressed aberrantly higher in breast tumor than non-tumor control tissues." (PMID 33809182, 2021). "Taken together, our data demonstrate a strong expression correlation between BACH1 and MCT1 in breast tumors from Black women, but not in those from White women, and mostly from the luminal A breast tumor subtype." (PMID 40710214, 2025). "Since our previous study demonstrated that BACH1 suppresses MCT1-dependent lactate oxidation pathways in TNBC, a negative correlation was expected between BACH1 and MCT1 expression in the basal-like subtype of breast tumors." (PMID 40710214, 2025).
triple-negative breast carcinoma (9 papers, 2015 to 2025). An invasive breast carcinoma which is negative for expression of estrogen receptor (ER), progesterone receptor (PR), and human epidermal growth factor receptor 2 (HER2). "This work identifies adapter protein syndecan-binding protein 1 (SDCBP, syntenin-1) as a BACH1 regulator in triple-negative breast cancer (TNBC) cells, controlling transcription of pro-metastatic and mitochondrial genes." (PMID 40263598, 2025). "BACH1 is a redox-sensitive transcription factor facilitating tumor progression in triple-negative breast cancer (TNBC)." (PMID 40263598, 2025). "Adapter protein SDCBP stabilizes BACH1 in triple-negative breast cancer cells, thus regulating transcription of pro-metastatic and mitochondrial genes." (PMID 40263598, 2025). "Here, we show that a heme-binding transcription factor, BACH1, negatively regulates lactate catabolic pathways in triple-negative breast cancer (TNBC) cells." (PMID 35406740, 2022). "A heme-regulating transcription factor, BTB and CNC homology 1 (BACH1), is more highly expressed in triple-negative breast cancer (TNBC), the most aggressive subtype of breast cancer." (PMID 35406740, 2022). "The level of Bach1 is also elevated in triple-negative breast cancer (TNBC), leading to lower activity of TCA cycle and decreased transcription of ETC genes." (PMID 34807950, 2021). "Previous studies have shown that BACH1 expression was significantly increased in hypertrophic human hearts, human carotid and coronary atherosclerotic plaques, and tumors from patients with triple-negative breast cancer and human epithelial ovarian cancer." (PMID 38129407, 2023). "Accordingly, recent reports demonstrated that targeting of BACH1 and mitochondrial metabolism may serve as an effective therapy for triple negative breast cancer." (PMID 32132179, 2020). "In particular, exposure of the triple-negative breast cancer (TNBC) cell lines, MDA-MB-231 and 1833, to HDACi trichostatin A (TSA) resulted in time-dependent induction of BACH1 mRNA, therefore demonstrating an inverse relationship between BACH1 and RKIP." (PMID 39335152, 2024).
glioblastoma (8 papers, 2016 to 2025). The most malignant astrocytic tumor (WHO grade IV). "BACH1 is strongly associated with immune responses in glioblastoma, especially M0 and M2 tumor-associated macrophages (TAMs)." (PMID 38321558, 2024). "In glioblastoma, elevated BACH1 correlates with an immunosuppressive microenvironment, suggesting therapeutic potential." (PMID 40963614, 2025). "In this study, we report that BACH1, a heme-binding protein that participates in transcriptional repression or activation, was significantly upregulated in glioblastoma tissues." (PMID 28000777, 2016). "BACH1 has been shown to confer resistance to temozolomide (TMZ) in glioblastoma." (PMID 38321558, 2024). "Except for the negative correlation to the infiltration of CD8+ T cells in low grade glioblastoma (LGG), the BACH1 expression level is positively related to the infiltration of the other five kinds of immune cells." (PMID 35651942, 2022).
Parkinson disease (8 papers, 2022 to 2025). A progressive degenerative disorder of the central nervous system characterized by loss of dopamine producing neurons in the substantia nigra and the presence of Lewy bodies in the substantia nigra and locus coeruleus. "Recent studies have identified HPPE as a promising inhibitor of BACH1 for treating Parkinson’s disease." (PMID 40312332, 2025). "Attenuation of parkinsonian pathologies by inhibition of Bach1 in the α-synuclein preformed fibril-induced mouse model of Parkinson’s disease." (PMID 40313365, 2025). "BACH1 has been proposed as a therapeutic target for several neurological diseases (e.g., Parkinson’s disease, multiple sclerosis), and PRR5 is part of the mTORC2 protein complex that is decreased in the AD brain at the protein level." (PMID 38557897, 2024). "Despite their therapeutic potential for a variety of conditions, including Huntington's and Parkinson's disease, spinal cord injury, ischemia/reperfusion injury, pulmonary fibrosis, and cancer, only a few BACH1 inhibitors/degraders have been identified so far." (PMID 35313207, 2022). "In that regard, we have reported a chemical derivative of cannabidiol with dual activity and protective effects in a cellular model of Huntington's disease and a recent work characterised a novel dual BACH1/KEAP1 inhibitor with protective effects in a Parkinson's model." (PMID 35313207, 2022). "BACH1 has recently gained visibility as a potential therapeutic target against a variety of conditions ranging from Parkinson's disease, bone destructive diseases, non-alcoholic steatohepatitis, atherosclerosis, insulin resistance, coronary artery disease and aging related conditions." (PMID 35313207, 2022). "Ablation of BACH1 reduces MPTP‐induced oxidative stress and neuroinflammationDeletion of BACH1 stimulates ARE‐mediated neuroprotective pathways, and upregulation of many Non‐ARE genes, which related to neuronal cell survival and beneficial for Parkinson's patients." (PMID 39887888, 2025).
pulmonary fibrosis (8 papers, 2017 to 2025). Chronic progressive interstitial lung disorder characterized by the replacement of the lung tissue by connective tissue, leading to progressive dyspnea, respiratory failure, or right heart failure. "A previous study showed that Bach1-deficient mice was more resistant to the oxidative stresses associated with hyperoxia lung injury, nonalcoholic steatohepatitis, and cardiovascular disease, as well as bleomycin-induced pulmonary fibrosis." (PMID 39905004, 2025). "In pulmonary fibrosis, BACH1 expression is upregulated and BACH1 knockdown ameliorates fibrosis and inflammation by inhibiting the ERK signal pathway." (PMID 37228820, 2023). "The progression of pulmonary fibrosis can be slowed down by regulating EMT through Bach1, ZEB1, NDRG1, erastin, liproxstatin-1, Cav-1 and other ferroptosis-related genes or proteins." (PMID 36672671, 2023). "In a pulmonary fibrosis mouse model, knockdown of Bach1 reduced oxidative injury and inflammation in lung tissues and cells and ameliorated lung fibrosis by blocking the Erk pathway." (PMID 37602966, 2023). "PFD promotes NRF2 recovery by regulating the NRF2/BACH1 balance, such as inhibiting BACH1 in bleomycin-induced pulmonary fibrosis and TGF-β1-induced rodent models of lung fibroblasts." (PMID 35721561, 2022). "In summary, we draw the conclusion that the antioxidant pathogenisis of prifenidone in pulmonary fibrosis in BLM-induced mice via the regulation of Nrf2/Bach1 balance that resulted in inhibition of Bach1 and promotion of Nrf2 or Nrf2 dependent antioxidants." (PMID 28420366, 2017). "Moreover, BACH1 appears to show an adverse role in diseases such as neurodegenerative diseases, gastrointestinal disorders, leukemia, pulmonary fibrosis, and skin diseases." (PMID 39887888, 2025). "Similarly, mice were subjected to bleomycin administration to develop pulmonary fibrosis that suffered oxidative injury, and Bach1 expression in the lung tissue was significantly increased." (PMID 37602966, 2023). "BACH1 suppression relieves fibrosis and inflammation by blocking the ERK signaling.BACH1 silence impedes oxidative stress and BLM‐inducing the M2 macrophage phenotype through activating the TGFβ/SMAD signaling to alleviates pulmonary fibrosis." (PMID 39887888, 2025). "Our previous study supported that and Bach1 knockout by siRNA enhanced the expression of Nrf2 dependent antioxidants in the TGF-β1 induced MLF and in mice of BLM induced pulmonary fibrosis." (PMID 28420366, 2017). "PFD inhibited Bach1 mRNA and protein expressions in mouse lung fibroblasts induced by TGF-β1 and lung tissues with pulmonary fibrosis induced by bleomycin." (PMID 28420366, 2017). "This demonstrated the influence of PFD on Nrf2/Bach1 equilibrium and expression of Nrf2-dependent antioxidants in TGF-β induced MLF and mice with BLM-induced pulmonary fibrosis." (PMID 28420366, 2017). "In addition, present study showed that the mRNA and protein expression levels of Nrf2, Ho-1, and Gpx1 in mouse pulmonary fibrosis induced by BLM were significantly increased, but in Bach1 were significantly decreased with PFD treatment for 4 weeks." (PMID 28420366, 2017).
atherosclerosis (7 papers, 2014 to 2025). A disease characterized by the build-up of fatty material and calcium deposition in the arterial wall resulting in partial or complete occlusion of the arterial lumen. "BACH1 is closely associated with cardiovascular diseases and contributes to angiogenesis, atherosclerosis, restenosis, pathological cardiac hypertrophy, myocardial infarction, and ischemia/reperfusion (I/R) injury." (PMID 39887888, 2025). "Bach1 binds to heme-responsive elements inhibiting the binding of Nrf2,41 with global deficiency in Bach 1 associated with reduced atherosclerosis." (PMID 29596571, 2018). "BACH1's upregulation is also seen in the carotid plaques of individuals with cerebrovascular symptoms, suggesting a potential role in atherosclerosis progression." (PMID 39887888, 2025).
colon carcinoma (7 papers, 2018 to 2024). "Increased BACH1 levels were positively associated with tumor progression in colon cancer." (PMID 37228820, 2023). "In BRAF (V600E) mutant skin and colon cancer, a complex comprising BACH1 and MAFG is formed, which is promoted by B-Raf proto-oncogene variant BRAF (V600E)." (PMID 38321558, 2024). "BACH1 siRNA produces similar effects in prostate and HT-29 colon cancer cells, including inhibition of invasion and migration." (PMID 38321558, 2024). "In colon cancer, BACH1 expression increases and promotes cancer cell migration by increasing the expression of metastasis-related genes including MMP-1, MMP-9, MMP-13, SNAIL1, CXCR4, and HMGA2." (PMID 37228820, 2023). "Another study demonstrated that BACH1 expression was lowest in adenomas, high in colon cancer tissues, and highest in normal tissues adjacent to colon cancer tissues." (PMID 37228820, 2023). "The phosphorylation of BACH1 is highly expressed in primary cancer tissues of colon cancer (phosphosites S196, S388, S445), LUAD (phosphosites T410, S443)." (PMID 35651942, 2022). "Bach1 silencing significantly inhibited the migration of colon cancer cells by inhibiting metastasis-related genes." (PMID 34949193, 2021). "Long non-coding RNA NEAT1 directly binds to let-7g-5p, which targets and upregulates BACH1 to facilitate EMT and cell growth of colon cancer." (PMID 37228820, 2023). "However, one study showed that the proliferative capacity of colon cancer cells was not affected by BACH1 knockdown in vitro." (PMID 37228820, 2023).
glioma (7 papers, 2016 to 2025). A benign or malignant brain and spinal cord tumor that arises from glial cells (astrocytes, oligodendrocytes, ependymal cells). "In addition, The expression of Bach1 was increased in glioma cells and was strongly associated with EMT." (PMID 38267442, 2024). "Upregulation of Bach1, a transcription factor regulating heme oxygenase-1 (HO-1) which catalyzes the breakdown of heme into iron, correlated with EMT and ferroptosis sensitivity in glioma cells, suggesting Bach1 as a potential marker of ferroptosis susceptibility in glioma patients." (PMID 39188677, 2024). "Upregulation of Bach1 is associated with EMT in glioma cells." (PMID 37598126, 2023). "In glioma, overexpression of BACH1 enhances the expression of CDH2, SNAI2, and CD44 in U87 cells to promote the EMT." (PMID 38321558, 2024). "More significantly, proteomic study showed that Bach1’s principal method of glioma invasion promotion depends heavily on the extracellular matrix (ECM)." (PMID 37598126, 2023). "The important glioma invasion regulator Bach1 has been found to coordinate a number of ECM-related activities." (PMID 37598126, 2023). "In addition, RCC2 enhances glucose metabolism through BACH1-dependent transcriptional upregulation of hexokinase II in glioma." (PMID 39908861, 2025). "BACH1 modulates extracellular matrix (ECM) remodeling to facilitate glioma invasion." (PMID 38321558, 2024). "Bach1 overexpression also lowered the requirement for glioma ferroptosis induction." (PMID 37598126, 2023). "Drugs that induce ferroptosis may enable the transition from Bach1 high expression induced tumor invasion to tumor suppression in gliomas." (PMID 37598126, 2023). "Notably, the development of ferroptosis is inhibited by overexpression of Bach1 in glioma cells." (PMID 38267442, 2024). "In addition, BACH1, stabilized by the regulator of chromatin condensation (RCC2) at the C-terminal, induces the upregulation of HK2, which drives glioma progression." (PMID 38321558, 2024). "The TCGA database of glioma showed that BACH1 levels were higher in GBM than nontumor brain tissue (NBT), and this result was verified by the data from clinical samples." (PMID 28000777, 2016).